HDAC7 (histone deacetylase 7)
Diseases named in the same sentence as HDAC7 in open-access papers (continued):
Sharing a sentence is not in itself a finding about the gene and the disease.
severe combined immunodeficiency (1 paper, 2020). Severe combined immunodeficiency (SCID) comprises a group of rare monogenic primary immunodeficiency disorders characterized by a lack of functional peripheral T lymphocytes resulting in early-onset severe respiratory infections and failure to thrive. "Moreover, we established pre-B-ALL xenograft nonobese diabetic/severe combined immunodeficiency (NOD/SCID) model using primary MNCs from one BCR-ABL1− pre-B-ALL patient who overexpressed HDAC7 for testing the antitumor activity of CC1007 in vivo." (PMID 32913188, 2020).
status epilepticus (1 paper, 2016). Status epilepticus is defined as a continuous seizure lasting more than 30 min, or two or more seizures without full recovery of consciousness between any of them. "On the other hand, increases in HDAC5 expression and decreases in HDAC7 expression during the acute status epilepticus may have a role in regulating expression of seizure‐related genes by specifically acetylating histones." (PMID 26603269, 2016).
steatosis (1 paper, 2023). Increased lipid within the cytoplasm of cells. "Correlations between HDAC7 and the progression of chronic liver disease have been widely studied, from simple steatosis to hepatic cell activation to cancer." (PMID 35303381, 2023). "Therefore, HDAC7 may contribute to hepatic steatosis by inhibiting NUR77 expression, thus promoting lipid accumulation in hepatocytes." (PMID 35303381, 2023). "Finally, gene expression analysis of tumorous livers from Trim24−/− mice, which spontaneously progress from steatosis to HCC, revealed that Hdac7 expression was elevated compared to non‐tumorous tissues." (PMID 35303381, 2023).
tauopathies (1 paper, 2025). "HDAC7 inhibition regained ac-K310 levels in both preventative and treatment cohort PS19 mice, combined with the attenuated tau pathology by HDAC7 intervention, emphasizing the functional importance of ac-K310 in the protection of tauopathy." (PMID 39806423, 2025). "Our findings suggest that upregulation of HDAC7 induces AD-like tau pathologies via deacetylating TFEB and inhibiting lysosomal biogenesis in astrocytes, and downregulating HDAC7-TFEB signaling is promising for arresting AD and other tauopathies." (PMID 39806423, 2025). "Our findings highlight the significance of astrocytes in the removal of tau protein via the HDAC7-TFEB lysosomal pathway, indicating its potential as a therapeutic target for the treatment of AD and other tauopathies." (PMID 39806423, 2025).
temporal lobe epilepsy (1 paper, 2016). A localization-related (focal) form of epilepsy characterized by recurrent seizures that arise from foci within the temporal lobe, most commonly from its mesial aspect. "Beyond this, striking similarities between both temporal lobe epilepsy models such as fast decreases in HDAC7 and 10 mRNAs during the acute status epilepticus were observed, notably also in the contralateral hippocampus not affected by neurodegeneration." (PMID 26603269, 2016).
urothelial bladder cancers (1 paper, 2023). "Mutations in multiple HDAC genes have been identified in urothelial bladder cancers, leading to the overexpression of HDAC1, HDAC2, and HDAC8, as well as the under-expression of HDAC5 and HDAC7." (PMID 36980741, 2023). "HDACs have also been studied in non-urothelial bladder cancer, with one study finding HDAC4, HDAC7, and HDAC9 to be overexpressed in basal-squamous bladder cancer." (PMID 36980741, 2023).
uterine cancer (1 paper, 2021). Primary or metastatic malignant neoplasm involving the uterine corpus and/or the cervix. "In line with our report, it has been shown that SAHA can down-regulate HDACs class I (HDAC2 and 3) and class II (HDAC7) resulting in p21WAF1 upregulation and apoptosis induction in uterine cancer." (PMID 34319031, 2021). "In uterine cancer, it has been reported that SAHA efficiently suppresses MES-SA uterine sarcoma cell growth by down-regulation of HDACs class I (HDAC2 and 3) and class II (HDAC7)." (PMID 34319031, 2021).
viral infection (1 paper, 2025). "Western blot analysis and immunofluorescence confirmed a significant reduction in HDAC7 expression following viral infection." (PMID 41229730, 2025).
tumor (61 papers, 2006 to 2026). "We examined HDAC1 and HDAC7 expression in postoperative tumor specimens and assessed their association with overall prognosis." (PMID 41444923, 2025). "Our data demonstrating that HDAC7 promotes aggressive behaviors and tumor progression led us to examine the underlying mechanisms." (PMID 40465706, 2025). "This confirms high immune infiltration and stroma presence in the tumor tissues associated with HDAC7-high and HDAC2-low expression." (PMID 39063083, 2024). "Tumor metastasis is closely associated with tumor angiogenesis, and HDAC7 plays vital roles in vascular repair, regeneration, and stability maintenance." (PMID 38827027, 2024). "On the other hand, class II HDACs, particularly HDAC7, are associated negatively with pluripotency markers’ expression in most tumor types, except for OCT4 (encoded by POU5F1), and NANOG in KIRC, KIRP, LGG, LUAD, LUSC, PRAD, and THCA." (PMID 39063083, 2024). "Animal studies on orthotopic xenograft tumors have shown that causing inhibition of HDAC7 can lead to a 3-fold reduction in tumor volume." (PMID 39068393, 2024). "A more recent study profiling gene expression in patients with acute promyelocytic leukaemia found that HDAC7 was co‐expressed with the tumour‐associated gene SHB, again correlating with poor survival." (PMID 35303381, 2023). "Now we demonstrate that loss of Hdac7 resulted in significantly enhanced Stat3 acetylation in both mouse primary tumors and human tumor cell lines." (PMID 29126425, 2017). "The data revealed that most of the PA tumors analyzed (25/29, 86%) showed increased expression of HDAC7 encoding gene when compared to CP and B tumor samples, in agreement with our previous observations." (PMID 25275504, 2014). "Higher tumor stages were associated with elevated HDAC7 expression levels as well." (PMID 38827027, 2024). "Some evidence suggests that HDAC7 may have causal roles in driving tumour growth and/or progression, for example by promoting oncogenic signalling and/or driving chronic inflammatory responses." (PMID 35303381, 2023). "HDAC4 and HDAC7 have been implicated in tumour growth, metastasis, and chemosensitivity." (PMID 28883618, 2017). "Mechanistic study revealed that Hdac7 mutation in mouse lung tumors or HDAC7 depletion in human tumor cell lines resulted in significantly enhanced acetylation and tyrosine-phosphorylation of Stat3 and HDAC7 protein directly interacted with and deacetylateed STAT3." (PMID 29126425, 2017). "Thus, the downregulation of both SWI/SNF and PRC2 complex factors but upregulation of HDAC7 suggests EZH2-associated platinum resistance may reflect increased tumor stemness." (PMID 34140011, 2021). "Complementary experiments using Western blotting and anti-HDAC7 specific antibodies reacted with total extracts from different tumor cell populations were performed to examine whether the alteration of HDAC7 gene expression was associated with a modification of HDAC7 protein synthesis." (PMID 25275504, 2014). "Mechanistically, OLIG2 recruited HDAC7 to repress CXCL10 transcription, inducing STAT3 activation in tumor-associated macrophages (TAMs) and decreasing CD8+ T cell infiltration and activation." (PMID 41591814, 2026). "We validated HDAC7 expression in 40 paired BCa tissues, finding that HDAC7 was significantly upregulated in tumor tissues compared with adjacent normal tissues at both mRNA and protein levels." (PMID 41444923, 2025). "In conclusion, our studies confirmed that DNMT3a acted as a tumour promoter to induce malignant progression of LUAD by upregulating HDAC7 and further inducing the upregulation of ZEB1 and c-Myc." (PMID 39990668, 2025). "To verify this finding, we analysed HDAC7 protein expression and the clinical significance of HDAC7 by IHC staining in a paraffin-embedded tissue microarray containing 119 paired tumour and normal tissue samples." (PMID 39990668, 2025).
tumor (continued). "High levels of HDAC7 have been shown to correlate with tumour progression and poor prognosis in breast cancer and lung cancer." (PMID 39990668, 2025). "Here, we demonstrate that HDAC7 promotes aggressive phenotypes and in vivo tumor progression in RCC." (PMID 40465706, 2025). "To investigate the effect of HDAC7 on CD8 + T cell anti-tumor function and immunotherapy sensitivity in vivo, we employed the HuNOG mouse model." (PMID 41444923, 2025). "Analysis of The Cancer Genome Atlas (TCGA) data revealed that HDAC7 expression was elevated in ten tumor types, including BCa, compared to normal tissues." (PMID 41444923, 2025). "In vivo, HDAC7 overexpression was verified to significantly increase the weight of subcutaneous tumours in the A549 DNMT3a knockdown group, as demonstrated by xenograft assays in nude mice." (PMID 39990668, 2025). "In our previous study, we found that c-Myc was upregulated via overexpression of HDAC7, which facilitated the escape of tumour cells from senescence and promotes their growth." (PMID 39990668, 2025). "These molecular insights highlight miR‐489 as a critical regulator of tumor suppression in gastric cancer, acting through the HDAC7/PI3K/AKT axis to modulate EMT and metastatic behavior." (PMID 40740483, 2025). "The anti-tumor activity of CD8 + T cells was significantly enhanced by co-culture with HDAC7 knockdown T24 cells and reduced by co-culture with HDAC7-overexpressing UMUC3 cells." (PMID 41444923, 2025). "HDAC7 was identified as a direct downstream target, and its silencing reversed the tumor‐promoting effects triggered by miR‐489 inhibition." (PMID 40740483, 2025). "In ESCC, HDAC7 can upregulate tumour progression mediated by WNT5A, regulate the expression of EMT-related molecules such as SNAIL and E-cadherin, and enhance the migration and invasion abilities of ESCC cells." (PMID 39990668, 2025). "Studies of HDAC7 in peripheral immune cells have shown that inhibiting HDAC7 can enhance the phagocytic ability of macrophages, leading to increased anti-tumor activity." (PMID 39806423, 2025). "The IHC assay assessed HDAC7 levels in tumor and adjacent normal tissues from HCC specimens at Shanghai Outdo Biotech Company, revealing markedly higher HDAC7 IHC scores in tumors versus normal tissues." (PMID 40861819, 2025). "Tumor volume and weight measurements indicated that HDAC7 knockdown significantly suppressed BCa growth and increased immunotherapy sensitivity in HuNOG mice." (PMID 41444923, 2025). "We further demonstrated for the first time the distinct trends of associations between class I and class IIA HDACs and anti-tumor immunity, with the expression of class I HDAC2 being negatively correlated and class IIA HDAC7 being positively correlated." (PMID 39063083, 2024). "In this ex vivo model, GBM tumour spheroids with HDAC7 knockdown exhibited reduced invasiveness in rat brain tissue compared to control GBM tumour spheroids." (PMID 39629136, 2024). "We found that HDAC7 facilitated a pro-tumour microenvironment by promoting the malignancy of GSCs and immunosuppressive transformation of MDMs by catalysing histone H3K27 deacetylation of SOX8 promoters to inhibit its expression." (PMID 39629136, 2024). "This strongly supports our first observation that HDAC2 is positively and HDAC7 is negatively correlated with tumor stemness." (PMID 39063083, 2024). "In this study, we aimed to employ immunohistochemistry to determine the protein level of HDAC7 in patient tissues, our data showed HDAC7 levels are upregulated in tumour tissues." (PMID 39431349, 2024). "To ascertain the ceRNA relationship between TTYH3 and HDAC7 in promoting cancer metastasis in vivo, we evaluated the effects of TTYH3‐3′UTR and HDAC7‐3′UTR on tumor cell colonization and dissemination by using nude mice hepatic metastasis models." (PMID 38827027, 2024). "We found that mice overexpressing TTYH3‐3′UTR or HDAC7‐3′UTR exhibited significantly larger subcutaneous tumor volumes and weights." (PMID 38827027, 2024).
tumor (continued). "HDAC7 has been demonstrated to play an important role in regulating malignant progression in a variety of tumours recently 39-41." (PMID 39629136, 2024). "Next, we evaluated the tumor microenvironment concerning HDAC2 or HDAC7 expression in all tested tumor types." (PMID 39063083, 2024). "We analyzed tumor immune infiltration, immune cell pathways, and immune checkpoint molecules to further explore the potential relationship between HDAC7 and immunity." (PMID 37960766, 2023). "In activated hepatic stellate cells, HDAC7 localised to the cytoplasm through an interaction with the tumour‐suppressor cylindromatosis (CYLD), thus derepressing hepatocyte growth factor (HGF) expression." (PMID 35303381, 2023). "Recent studies have shown that HDAC7 and c-Myc have a close relationship in promoting tumor aggression." (PMID 36653340, 2023). "Western blot analysis showed that c-Myc, which plays an indispensable role in tumor progression, was dramatically upregulated in the HDAC7 overexpression groups." (PMID 36653340, 2023). "By analysing two human datasets, the authors found that HDAC7 levels were also elevated in tumours from HCC patients by comparison to non‐tumour tissues." (PMID 35303381, 2023). "HDAC7 has also been pursued as a target in chronic lymphocytic leukaemia through reprogramming of macrophage functions to boost anti‐tumour responses." (PMID 35303381, 2023). "In this regard, HDAC7 repressed the transcription of a range of chemokines and cytokines, for example the anticancer cytokine IL‐24 that promotes tumour cell killing." (PMID 35303381, 2023). "To detect the expression of HDAC7 in CM, we conducted IHC staining analysis to investigate the HDAC7 level in a tissue microarray including 16 CM tumor-normal tissues, and it was significantly higher in CM tissues (P < 0.001)." (PMID 36653340, 2023). "In the present study, the IHC analysis results based on 16 paired CM tumors and normal samples showed that the HDAC7 level was significantly higher in CM tumor tissues." (PMID 36653340, 2023). "To identify HDAC7-related signaling pathways and immunity, we further explored the potential relationships between HDAC7 and immunity, focusing on 3 aspects: tumor immune infiltration, immune cell pathways, and immune checkpoint molecules." (PMID 37960766, 2023). "Overall, our studies first confirmed that HDAC7 functioned as a tumor promoter by enhancing CM cell proliferation and metastasis." (PMID 36653340, 2023). "The tumor immunity estimation resource and integrated repository portal for tumor immune system interactions databases were used to analyze the correlation between HDAC7 and DLBCL immune cell infiltration." (PMID 37960766, 2023). "Some scholars found that silencing HDAC7 can suppress the expression of c-Myc and further block cell cycle progression in Hela and MCF-7 cells, which demonstrates the close relationship between HDAC7 and c-Myc in tumor progression." (PMID 36653340, 2023). "miR-150, which is down-regulated in pro-B cells from Hdac7-null mice, is related to B cell development and performs tumor-suppressor functions in leukemic cells." (PMID 35904805, 2022). "Conversely, overexpression of FGF18 reversed the attenuated ability in tumor growth and metastasis mediated by downregulating HDAC7." (PMID 35277183, 2022). "We found the HDAC7 level was positively correlated to pTNM stage instead of differentiation, tumor invasion and lymphatic metastasis." (PMID 36163081, 2022). "HDAC5 showed decreased levels in tumor tissue while HDAC7 was significantly increased in tumor tissue." (PMID 36227941, 2022). "In Hepatic Stellate cell (HSC) cells, cytokines such as IL-6 and TNF promote the binding of HDAC7 to the anti-tumor gene cylindromatosis (CYLD), which recruits HDAC7 to the nucleus near the promoter of the hepatocyte growth factor (HGF)." (PMID 36148005, 2022).
tumor (continued). "A knockdown of HDAC7 led to a reduction of sphere-forming ability and in vivo tumor growth of classic CSC phenotypes, and HDAC7 levels of expression in CSCs were also found to be higher than in non-stem cancer cells." (PMID 35563709, 2022). "Although we verified the function of HDAC7 in aggravating NSCLC proliferation and metastasis, the underlying mechanisms driving tumor progression need to be further elaborated." (PMID 35277183, 2022). "In NSCLC, histone deacetylases 7 (HDAC7) showed an elevated expression in tumor tissues and high HDAC7 expression related to the poor prognosis." (PMID 36582601, 2022). "The upregulated HDAC7 expression was positively correlated to larger tumor size, T stage, lymphatic invasion, distant metastasis, tumor–node–metastasis (TNM) stages, and tumor differentiation." (PMID 35277183, 2022). "Subcutaneous tumor formation experiment was performed to detect the effects of HDAC7 knockdown on the in vivo growth of HK1 and 5–8F NPC cells." (PMID 32376822, 2020). "Histone deacetylase HDAC7 is proved to be involved in a variety of cellular physiological processes and as a novel target for tumor therapy." (PMID 32284070, 2020). "Overexpressing HDAC7 alone was sufficient to increase tumor initiating capacity in vivo, indicating that HDAC7 is an essential epigenetic regulator to maintain CSC phenotype." (PMID 31277278, 2019). "Our studies demonstrate that HDAC7 functions as a tumor promoting factor by deacetylating STAT3, therefore reducing STAT3 activation." (PMID 29126425, 2017). "Consistent with the results of TUNEL and EdU labeling assay, more caspase-3 cleavage and less p-Histone H3 was observed in Hdac7+/−/K-Ras tumor cells respectively." (PMID 29126425, 2017). "This suggests a potential tumor suppressive function of HDAC7 in some other cancers and/or at different stages of cancer development." (PMID 29126425, 2017). "We demonstrated that the Hdac7 mutant-mediated tumor suppression was rescued by expressing dnStat3 in mouse lung tumors." (PMID 29126425, 2017). "The acetylation and phosphorylation of Stat3 were significantly enhanced in tumors from Hdac7+/−/K-Ras mice and HDAC7-depleted human tumor cell lines." (PMID 29126425, 2017). "The results showed that total tumor numbers on mouse lung surface and tumor burden were markedly reduced in Hdac7+/−/K-Ras mice compared with control mice." (PMID 29126425, 2017). "Here, our study results show that tumor number, tumor burden, and tumor size (unpublished data) were all decreased in Hdac7+/−/K-Ras mice." (PMID 29126425, 2017). "Immunofluorescence assays revealed a significant reduction of proliferation, as revealed by Ki67 staining, and increased apoptosis in tumor cells expressing HDAC7." (PMID 25675295, 2015). "PA samples showed statistically higher mean mRNA transcription levels for HDAC7 and HDAC2when compared to their counterpart biopsies taken at the tumor periphery (p = 0.0346, 0.0053, respectively)." (PMID 25275504, 2014). "In NSCLC, histone deacetylase 7 (HDAC7) promotes tumor proliferation and metastasis by activating the β-catenin/FGF18 pathway, suggesting that targeting HDAC7 or its associated signaling cascades may serve as a novel therapeutic strategy." (PMID 41268614, 2026). "Here, we demonstrate the role of HDAC7 in tumor progression using an orthotopic tumor model." (PMID 40465706, 2025). "Furthermore, we evaluated HDAC7’s role in tumor biology using orthotopic RCC models with CAKI-1 and SN12-PM6-1 cells." (PMID 40465706, 2025). "However, insight into the functional significance of HDAC7 expression on tumor progression has been limited to date." (PMID 40465706, 2025). "However, the roles and mechanisms of HDAC7 in BCa remain poorly characterized, and its function in tumor immune evasion and immunotherapy sensitivity is largely unexplored." (PMID 41444923, 2025).